TGFB1 (transforming growth factor beta 1)
Diseases named in the same sentence as TGFB1 in open-access papers (continued):
Sharing a sentence is not in itself a finding about the gene and the disease.
fibrosis (continued). "LEF inhibits osteopontin (OPN)/transforming growth factor beta 1 (TGF-β1)-mediated extracellular matrix deposition, tubular interstitial fibrosis, and tubular epithelial–mesenchymal transdifferentiation to reduce kidney injury in diabetic rats." (PMID 36111292, 2022). "TGFβ1 and pSmad3/Smad3 were significantly elevated in the diabetic animal model established in this study, which also suggested that the glomerular fibrosis of DKD was closely related to the TGFβ1/Smads pathway." (PMID 35126820, 2022). "Cardiac fibrosis is tightly dependent on transforming growth factor beta-1 (TGF-β1), contributing to cardiac fibroblast differentiation to myofibroblast." (PMID 34778418, 2021). "In this context, we have observed a significant reduction of COL1A1 and TGFB1 gene expressions through the addition of 2 μM amphotericin B in our fibrosis model with primary NHDFs supplemented with TGF-β1." (PMID 33096778, 2020). "We found that MA-35 reduced the fibrotic cytokines Tgfb1 and Fn1 and intestinal fibrosis by inhibiting the TGF-β1/Smad pathway in an AOM/DSS mouse model." (PMID 31484999, 2019). "It was reported that Smad3KO mice inhibit cardiac fibrosis, decreasing the expression of αSMA, TGFβ1, and TNFα." (PMID 31597354, 2019). "It is interesting to note that the IL-13 lung-fibrosis model is dependent on TGFβ1, whereas other IL-13-dependent models of fibrosis (e.g. S. mansoni) are not." (PMID 24713275, 2014). "It was shown that transforming growth factor beta 1 (TGFβ1) overexpression induces cardiac fibrosis, resulting in an increased collagen content in the heart." (PMID 24416594, 2013). "In a clinical study including of 30 patients with ALD, divided into four groups along clinical findings and liver histology, that are i), steatosis; ii), fibrosis; iii), hepatitis; and iv), cirrhosis, liver biopsies were tested for TGFB1, TGFB2, and TGFB3 gene expression by RT-PCR." (PMID 41109667, 2026). "Furthermore, the laminectomy group shows the highest mean expression of IL6 and TGFβ-1 in laminectomy rats than in the control group and other treated groups due to epidural fibrosis formation, which agrees with the prior studies." (PMID 40804422, 2025). "Furthermore, some studies have reported a tight correlation between the RUNX family and TGFB1 with fibrosis and CKD development." (PMID 38256206, 2024). "It was found that the overall effect of red quinoa powder produced more significant change than rutin in fibrosis and preserved the liver by inhibiting the route of inflammatory markers like tumor necrosis alpha and transforming growth factor beta 1 activities." (PMID 39055188, 2024). "Through histological, protein content, and transcript analysis approaches, we found that cardiac fibrosis‐related genes partly change, with significant TS‐associated increases in Tgfb1, but without changes in Col1a1 and Fn1." (PMID 36695670, 2023). "Notably, 3PO reduced PFKFB3 expression and inhibited the transforming growth factor-beta 1/mothers against the decapentaplegic homolog 2/3 (TGF-β1/SMAD2/3) signaling pathway to inhibit cardiac fibrosis after MI." (PMID 37509108, 2023). "However, there is interplay role of several factors including microRNAs (miRNAs) which acts as a potential regulator of cardiac fibrosis connected with TGFβ-1." (PMID 37306727, 2023). "TGFβ1 TG mice showed significantly elevated plasma concentration of corisin compared to WT mice, and the plasma concentration of corisin significantly correlated with the CT fibrosis score, Ashcroft fibrosis score, and the lung hydroxyproline content." (PMID 35322016, 2022). "In addition, the supplementation with carob extracts decreased the expression of the pro-fibrotic marker TGFβ1 and arterial vascular fibrosis in mice fed with a high fat/high sucrose diet and in rabbits with dyslipidaemia." (PMID 35204314, 2022).
fibrosis (continued). "Moreover, we demonstrated that tissue-specific ECM can provide key insights into liver fibrosis and pro-cancerogenic TGFβ1-induced EMT in fibroblastic stromal cells and cancer cells, respectively." (PMID 34638417, 2021). "Admittedly, it is difficult to distinguish whether AAV-shTGFβ1 increased liver regeneration by inhibiting hepatic fibrosis or inhibiting TGFβ1." (PMID 33754025, 2021). "Deficiency of TIMP3 led to extensive cardiac fibrosis through activation of TNF-α, TGFβ1 and downstream molecules Smad2/3 after pressure overload in mice, which could be inhibited by a TGFβ1 neutralizing antibody." (PMID 34778374, 2021). "In confirmation of our hypothesis, we show that specific CpGs within TGFβ1 (CpG2) and PDGFα (CpG3) are significantly more methylated in patients with mild fibrosis whereas PPARα (CpG3) and PPARδ (CpG2) show considerably less methylation in the same group." (PMID 25859289, 2015). "Fibrosis is one of the most undesirable side effects of TGFβ1 expression." (PMID 25236373, 2014). "At this timepoint, the simGCRsim-IR mice had elevated levels of cardiac fibrosis, inflammation, and hypertrophy markers Tgfβ1, Mcp1, Mmp9, and βmhc, suggesting that space-type IR may induce the cardiac remodeling processes that are commonly associated with diastolic dysfunction." (PMID 36982525, 2023). "Thrombospondins may also contribute to vascular fibrosis through TGFB1." (PMID 37841308, 2023). "Moreover, miR-1 overexpression also inhibited cardiac fibrosis and apoptosis by reducing the mRNA expression of transforming growth factor beta-1 (Tgfb1) and increasing protein expression of Bcl-2, while reducing the level of Bax, thereby altering the Bcl-2/Bax ratio." (PMID 38132140, 2023). "In the bleomycin-induced fibrosis models, the depletion of pDCs could reduce the collagen deposition in lung and skin tissues and downregulate the expression of profibrotic genes, such as TGFβ1." (PMID 34222222, 2021). "Given the importance of ROS overproduction in diabetic glomerular injury and mesangial fibrosis through TGFB1 upregulation, even delayed treatment with Tempol could decrease Tgfb1 mRNA, inhibit mesangial cell fibrosis, and decrease albuminuria in diabetic rodents." (PMID 30397232, 2018). "Infection by S. mansoni eggs results in a granuloma-associated fibrosis that, in contrast to injury-induced fibrosis, appears to be driven by the Th2 cytokine IL-13, with little-to-no role for the traditional fibrotic stimulant TGFβ1." (PMID 24713275, 2014). "Interestingly, IL-13 modulates TGFβ1 signalling during airway fibrosis, and alcohol’s priming effect for increased IL-13 signalling may play a role in lung transplantation related injury." (PMID 23547562, 2013). "Furthermore, we evaluated if andrographolide could prevent the differentiation of fibroblasts to myofibroblasts in vitro, given that the transforming growth factor beta-1(TGF-β1) stimulated persistence of myofibroblasts in the cornea is a primary component of fibrosis." (PMID 36291655, 2022). "We observed similar expression patterns in both Ccsp-TGFβ1-TG mice and BLM-induced fibrosis model mice." (PMID 34011956, 2021). "Fibrosis is the main feature of ESRD, and it is likely influenced by Transforming Growth Factor Beta1 (TGFβ1)." (PMID 25279306, 2014). "APN interferes with the expression of TIMP1 and TGFB1 in IBD by targeting AdipoR2, so emodin succinate monoethyl ester (ESME), an AdipoR2 agonist possibly recedes the severity of colonic fibrosis in UC and fistulae in CD by restoring balance of TIMP1 and TGFB1." (PMID 40713669, 2025). "In summary, we found platelet-derived TGFβ1 does not significantly drive pulmonary inflammation and fibrosis in the animal model of bleomycin-induced PF." (PMID 37643008, 2023).
fibrosis (continued). "In line with previousstudies showing that nintedanib and pirfenidonereduce TGFβ1-induced proliferation of human fibroblasts, we observed that in our PIC-RGD hydrogel fibrosis model both nintedaniband pirfenidone significantly reduced myofibroblast proliferation." (PMID 35468292, 2022). "Fibrosis in sWAT and high levels of genes from ECM, such as TGFB1 andFN1." (PMID 36354755, 2022). "This is supported in our study by the substantial reduction in the TGFb1 level in the mild fibrosis depleted transplanted vs. mild fibrosis nondepleted transplanted group (p value < 0.001)." (PMID 30631109, 2019). "Glutamyl-prolyl-tRNA-synthetase (EPRS) has been identified as a target for anti-fibrosis therapy, but the link between EPRS and TGFβ1-mediated IPF pathogenesis remains unknown." (PMID 30524284, 2018). "Furthermore, galangin blocked transforming growth factor beta 1 (TGF-β1) and alpha-smooth muscle actin (α-SMA) expression, demonstrating antioxidant and anti-fibrotic properties, thus providing a potential preventive treatment for fibrosis and liver cirrhosis." (PMID 40142029, 2025). "Furthermore, data show that adiponectin impedes hepatic fibrosis, by inhibiting platelet-derived growth factor (PDGF) stimulation and downregulating the transforming growth factor beta 1 (TGF-β1), whilst as NAFLD progresses, adiponectin levels appear to decline." (PMID 38524631, 2024). "The fractal dimension distributions in the Ad-TGFβ1-induced experiment did not have values as high as in the bleomycin-induced experiment, indicating that the Ad-TGFβ1 model of fibrosis might have less complex collagen structure." (PMID 37938346, 2024). "However, other studies found that the expression of miR-122 was downregulated in patients with severe fibrosis (SF) when compared with non-SF patients and controls, possibly through the upregulation of transforming growth factor beta 1 (TGF-b1)." (PMID 27504893, 2016). "Indeed, exposure of PCLS from patients with fibrosis or end-stage cirrhosis to Ac-6-FP resulted in a decrease in MAIT cell activation and reduced the expression of fibrogenic genes, including COL1A1 and COL1A2, ACTA2, and TGFB1, together with the number of fibrogenic cells." (PMID 37005415, 2023). "Thus, activation of a TSP1-mediated TGFβ1/Smads pathway plays an important role in marcovascular remodeling in T2DM, and valsartan may hold promise for blocking the pathway and ameliorating vascular fibrosis in diabetes." (PMID 25884585, 2015).
pancreatic cancer (867 papers, 2001 to 2026). "A study found that S100A4 was associated with the low survival rate of pancreatic cancer, and TGFβ1 promoted EMT and increased invasiveness by up-regulating S100A4 expression level." (PMID 38431306, 2024). "Concordant with the in silico data suggesting LINC00261 association with EMT, only TGFβ-responsive lung and pancreatic cancer cell lines significantly downregulated LINC00261 expression upon exposure to TGFβ-1 for 24, 48, and 72 h." (PMID 32414223, 2020). "There is growing evidence that the desmoplastic response associated with pancreatic cancer is representative of dysregulated normal injury repair processes that include TGFβ1-stimulated expression of type I collagen and other ECM proteins." (PMID 16622460, 2006). "Many growth factors expressed by human pancreatic carcinoma cells have the ability to induce fibroblast proliferation, for example, transforming growth factor β1 (TGFβ1) and fibroblast growth factor (FGF) 2 and are associated with advanced tumour stage and decreased survival." (PMID 23125850, 2012). "Exposure of pancreatic cancer cells, specifically aspc-1 and panc-1, to TGFβ1 triggered distinct changes in their characteristics." (PMID 38939095, 2024). "TGFB1 also plays a significant role in pancreatic cancer chemoresistance, with activation of pancreatic stellate cells leading to excessive ECM deposition and fibrosis impairing drug delivery to cells." (PMID 39660530, 2024). "For example, overexpression of EGLN3 through the transforming growth factor beta 1 (TGF ß1) pathway has been found to be linked to cancer cell invasion, metastasis, and poor prognosis in pancreatic cancer." (PMID 39682235, 2024). "Conditioned media obtained from PSCs treated with TGFβ1, 5-FU, CTRL miR, miR-15a, and 5-FU-miR-15a alone and in combination with TGFβ1 were used as chemoattractants for pancreatic cancer cell invasion." (PMID 36835366, 2023). "5-FU-miR-15a alone and in combination with TGFβ1 most efficiently reduced the invasion of pancreatic cancer cells as compared to appropriate controls." (PMID 36835366, 2023). "Pancreatic cancer cells released Transforming growth factor beta 1 (TGFβ1) and induced Pancreatic stellate cells (PSCs) to express FAP." (PMID 37316886, 2023). "Among a variety of chemokines/cytokines known to recruit and/or generate MDSCs in tumor sites, we found significant elevations in Cxcl1, Cxcl2, Csf2, and Tgfb1 in the pancreatic tumor tissues of PKR mice." (PMID 37814340, 2023). "Identification of lncRNAs regulated by TGFB1, an EMT-promoting factor, showed that HULC is among the TGFB1-induced lncRNAs in pancreatic cancer cells." (PMID 35055115, 2022). "Blockade of TGFβ1 significantly reversed TMEM158 overexpression-induced pancreatic cancer cell metastasis and epithelial-mesenchymal transition." (PMID 35945754, 2022). "The blockade of TGFβ1 by soluble TGFβRII protein also reduced pancreatic cancer cell metastasis in an orthotopic mouse model." (PMID 34360896, 2021). "The TGFβ1 neutralizing antibody abolished the effect of Arl4c on promoting the stemness and drug resistance of pancreatic cancer cells." (PMID 34849465, 2021). "Several reports have already demonstrated the involvement of TGFβ1 in the regulation of some cell types’ intracellular mechanisms, including lung, embryonic fibroblasts, and pancreatic cancer cells, through a Ca2+ -dependent pathway." (PMID 34063470, 2021). "To date, the most potent fibrogenic factor involved in PSC-mediated fibrosis, as well as in the interaction with the pancreatic cancer cells, is the TGFβ1." (PMID 34063470, 2021). "NRP1 was also reported to contribute to pancreatic cancer aggressiveness by promoting transforming growth factor beta 1 (TGFβ1)-induced fibrosis and endothelial-to-mesenchymal cell transition, a process that serves as an important source of fibroblasts." (PMID 33121034, 2020).
pancreatic cancer (continued). "Several studies connect CD36 and TSP-1 to the TGFβ1 signaling, linking this to pancreatic cancer, providing information on another molecule involved in the process, PAI-1, which is upregulated in pancreatic cancer cells." (PMID 32781778, 2020). "A recent study by Guo revealed that transforming growth factor-beta 1 (TGFβ1) treatment can induce mitochondrial morphologic variations in connection with a shift from epithelial to mesenchymal phenotype of pancreatic cancer cells." (PMID 32793478, 2020). "Critical cytokines such as transforming growth factor beta 1 (TGF-β1) are known to drive epithelial-to-mesenchymal (EMT) transition in pancreatic cancer cells." (PMID 31772762, 2019). "Pancreatic cancer cells also release fibrogenic mediators such as transforming growth factor β1 (TGFβ1) which stimulate the synthesis and deposition of ECM components by activated PSCs." (PMID 29903049, 2018). "In contrast, recent work demonstrated that TGFβ1 drove a pro-tumourigenic phenotype in pancreatic cancer." (PMID 27515461, 2016). "Since Smad4 is critically involved in TGFβ1 signaling, it is reasonable to assume that there is a close link between these calcium binding proteins and TGFβ1 in pancreatic cancer." (PMID 24670043, 2014). "In human pancreatic cancer cells, TGFβ1, overexpression correlates with collagen I levels, suggesting that TGFβ1 is directly able to elicit the desmoplastic reaction, an observation which has been confirmed in experimental models of pancreatic cancer." (PMID 23125850, 2012). "In fact, it has been shown in vitro that TGFβ1 upregulates type I collagen expression in pancreatic cancer." (PMID 16622460, 2006). "Additionally, the analysis of the publicly available microarray dataset GSE71729 confirmed a positive correlation between CCN1 and ENPP2, as well as TGFB1 expression in pancreatic cancer patients." (PMID 39273316, 2024). "Research into TGFB1 axis modulation in pancreatic cancer is expanding." (PMID 39660530, 2024). "TGFB1 signaling in pancreatic cancer is complex, having both an anti‐ and pro‐tumorigenic function." (PMID 39660530, 2024). "Interestingly, we found a common hub gene TGFB1 between T2DM vs. pancreatic cancer and T2DM vs. liver cancer patients, which significantly affects survival." (PMID 38114687, 2023). "In addition, pancreatic stellate cells mainly undergo FAP overexpression by inducing pancreatic cancer cells-released TGFβ1." (PMID 37316886, 2023). "Importantly, we showed that condition media obtained from PSCs treated with 5-FU-miR-15a or TGFβ1, and 5-FU-miR-15a significantly inhibit the invasion of pancreatic cancer cells." (PMID 36835366, 2023). "Studies of the mechanism have demonstrated that the activation of TGFβ1 and PI3K/AKT signals may be the aggressive cause of TMEM158 triggering pancreatic cancer." (PMID 35945754, 2022). "Expanding on our previous findings, we have shown that ectopic expression of the pancreatic lineage specifier PDX1 reduces the migration potential of pancreatic cancer cells by increasing their adhesiveness and reducing the sensitivity to TGFβ1-induced epithelial-mesenchymal transition." (PMID 34503200, 2021). "Activated PSCs are also characterized by their ability to produce and secrete a variety of cytokines and growth factors, such as TGFβ1, leading to the perpetuated activation of PSCs but also participating in the permanent dialogue with the pancreatic cancer cells." (PMID 34063470, 2021). "TGFβ1 is a main factor inducing immunosuppression in tumor microenvironment of pancreatic cancer, and inhibition of TGFβ1 strategy may provide a new opportunity for the treatment of pancreatic cancer." (PMID 34249724, 2021). "Indeed, TIPE2 inhibited the growth of pancreatic cancer in mice subcutaneous tumor model and the expression of TGFβ1 in tumor cells was suppressed." (PMID 34249724, 2021). "PPP1R1B, SMARCA4, and TGFB1 have well-described roles in the pathogenesis of pancreatic cancer." (PMID 34009124, 2021).